OR5W2 (olfactory receptor family 5 subfamily W member 2)
Description:
Odorant receptor.
Synonyms: OR5W2P; OR5W3P
Tractability: Antibody: UniProt places it where antibodies can reach, with medium confidence; UniProt predicts a signal peptide or a membrane-spanning region; its Gene Ontology location is reachable by antibodies, with medium confidence.
Gene: Protein-coding gene on chromosome 11 (55,913,650 to 55,914,582, reverse strand). Ensembl gene ENSG00000187612.
Subcellular location: Cell membrane
Pathways (Reactome):
Sensory Perception: Expression and translocation of olfactory receptors
Gene Ontology:
Molecular function: odorant binding; olfactory receptor activity; G protein-coupled receptor activity
Biological process: sensory perception of smell; detection of chemical stimulus involved in sensory perception of smell; G protein-coupled receptor signaling pathway
Cellular component: plasma membrane; membrane
Genetic constraint (gnomAD): Missense variants: 435 observed, 367.86 expected, observed/expected ratio (o/e) 1.18, 90% interval 1.09 to 1.28. Synonymous variants: 163 observed, 141.64 expected, observed/expected ratio (o/e) 1.15, 90% interval 1.01 to 1.31.
Homologues: Orthologues: chimpanzee OR5W2 (98% identical), macaque OR5W2 (94% identical), dog OR5W2B (84% identical), dog OR5W2 (83% identical), rat Or8w1 (80% identical), mouse Or5w8 (79% identical), rat Or5w8 (79% identical), mouse Or8w1 (79% identical), rat Or5w8b (79% identical), rat Or8w1b (78% identical). Paralogues in human: OR5AP2 (56% identical), OR5AR1 (55% identical), OR5C1 (55% identical), OR5J2 (55% identical), OR5AS1 (54% identical), OR5I1 (54% identical), OR5L1 (53% identical), OR5A1 (53% identical), OR5B21 (53% identical), OR5L2 (52% identical), OR5D18 (52% identical), OR8U1 (52% identical), and 84 more.
Diseases named in the same sentence as OR5W2 in open-access papers:
OR5W2 is named in the same sentence as 1 disease in open-access papers, as found by Europe PMC text mining. Sharing a sentence is not in itself a finding about the gene and the disease.
OR5W2 shares sentences with these, for which no sentence is quoted: prostate carcinoma (1 paper).